BLVRB (biliverdin reductase B)
Description:
Enzyme that can both act as a NAD(P)H-dependent reductase and a S-nitroso-CoA-dependent nitrosyltransferase. Promotes fetal heme degradation during development. Also expressed in adult tissues, where it acts as a regulator of hematopoiesis, intermediary metabolism (glutaminolysis, glycolysis, TCA cycle and pentose phosphate pathway) and insulin signaling. Has a broad specificity oxidoreductase activity by catalyzing the NAD(P)H-dependent reduction of a variety of flavins, such as riboflavin, FAD or FMN, biliverdins, methemoglobin and PQQ (pyrroloquinoline quinone). Contributes to fetal heme catabolism by catalyzing reduction of biliverdin IXbeta into bilirubin IXbeta in the liver. Biliverdin IXbeta, which constitutes the major heme catabolite in the fetus is not present in adult. Does not reduce bilirubin IXalpha. Can also reduce the complexed Fe(3+) iron to Fe(2+) in the presence of FMN and NADPH. Acts as a protein nitrosyltransferase by catalyzing nitrosylation of cysteine residues of target proteins, such as HMOX2, INSR and IRS1. S-nitroso-CoA-dependent nitrosyltransferase activity is mediated via a 'ping-pong' mechanism: BLVRB first associates with both S-nitroso-CoA and protein substrate, nitric oxide group is then transferred from S-nitroso-CoA to Cys-109 and Cys-188 residues of BLVRB and from S-nitroso-BLVRB to the protein substrate. Inhibits insulin signaling by mediating nitrosylation of INSR and IRS1, leading to their inhibition.
Synonyms: FLR; SDR43U1; BVRB; HEL-S-10
Tractability: Small molecule: a structure with a bound ligand is known; a high-quality ligand is known; it has a high-quality binding pocket. Antibody: its Gene Ontology location is reachable by antibodies, with high confidence. PROTAC: ubiquitination databases record sites on it; its protein half-life has been measured; a small molecule that binds it is known.
Target class: Enzyme; Oxidoreductase
Gene: Protein-coding gene on chromosome 19 (40,447,765 to 40,465,826, reverse strand). Ensembl gene ENSG00000090013.
Subcellular location: Cytoplasm
Subcellular location (Human Protein Atlas): Cytosol; Nucleoplasm; Plasma membrane; Vesicles
Pathways (Reactome):
Cellular responses to stimuli: Cytoprotection by HMOX1
Metabolism: Heme degradation
Gene Ontology:
Molecular function: biliverdin reductase [NAD(P)H] activity; FMN reductase (NADH) activity; FMN reductase (NADPH) activity; peptidyl-cysteine S-nitrosylase activity; protein binding; riboflavin reductase (NADPH) activity
Biological process: heme catabolic process; megakaryocyte differentiation; negative regulation of insulin receptor signaling pathway
Cellular component: cytoplasm; cytosol; extracellular exosome
Genetic constraint (gnomAD): Loss-of-function variants: 27 observed, 21.47 expected, observed/expected ratio (o/e) 1.26, 90% interval 0.93 to 1.72. The upper end of that interval is the gene's LOEUF score, 1.72, which puts it in group 6 of 6, group 1 being the genes least tolerant of losing a copy. Missense variants: 274 observed, 281.18 expected, observed/expected ratio (o/e) 0.97, 90% interval 0.88 to 1.08. Synonymous variants: 128 observed, 121.77 expected, observed/expected ratio (o/e) 1.05, 90% interval 0.91 to 1.22.
Homologues: Orthologues: chimpanzee BLVRB (99% identical), macaque BLVRB (99% identical), guinea pig BLVRB (94% identical), mouse Blvrb (93% identical), rat Blvrb (93% identical), pig BLVRB (92% identical), dog BLVRB (81% identical), rabbit BLVRB (78% identical), tropical clawed frog blvrb (64% identical), zebrafish blvrb (62% identical), Drosophila melanogaster CG9471 (36% identical).